FOXP3 (forkhead box P3)
Diseases named in the same sentence as FOXP3 in open-access papers (continued):
Sharing a sentence is not in itself a finding about the gene and the disease.
ulcerative colitis (23 papers, 2013 to 2025). An inflammatory bowel disease involving the mucosal surface of the large intestine and rectum. "This study is aimed at investigating the association of ulcerative colitis (UC) with FOXP3 polymorphisms and its colonic expression in Chinese patients." (PMID 30918515, 2019). "In conclusion, we have shown that urinary potassium level is inversely associated with the disease activity in ulcerative colitis and in vitro data suggests that it suppresses inflammation by reducing the IL-17 and IFNγ and inducing the Foxp3 expression on Th17 cells." (PMID 29273710, 2017). "This study provides initial insights into potential transcription factors involved in the pathogenesis of ulcerative colitis (UC), specifically highlighting FOXP3, STAT6, and hsa-miR-186-5p." (PMID 40729322, 2025). "Ulcerative colitis (UC) pathogenesis is related to imbalance of immune responses, and the equilibrium between inflammatory T cells and Foxp3+ regulatory T cells (Tregs) plays an important role in the intestinal homeostasis." (PMID 28588584, 2017). "Third, only a limited set of immune markers (CD4, CD8, and IL-6) was analyzed; inclusion of additional cytokines and functional markers (e.g.,TNF-α, TGF-β, FOXP3, IL-17, granzyme B) could provide a more comprehensive understanding of immune regulation in ulcerative colitis." (PMID 41465205, 2025). "In addition, we demonstrated that the overexpression of Rbm47 enabled B cells to facilitate Foxp3+ regulator T-cell induction and reduce the severity of DSS-induced ulcerative colitis." (PMID 29844590, 2019).
gastritis (22 papers, 2008 to 2026). Inflammation of the stomach. "It has been previously demonstrated that FOXP3+ thymocytes are dramatically reduced in IL-2/IL-2R deficient mice and that neutralization of IL-2 using αIL-2 monoclonal antibody results in autoimmuno gastritis in mice." (PMID 23864893, 2013). "With regard to GC pathogenesis, Helicobacter pylori is its best-understood risk factor, with gastric biopsy showing increased numbers of Foxp3+ Tregs in H. pylori-infected gastritis and GC patients." (PMID 32927747, 2020). "Using the proposed models, the likelihood for a patient to have gastritis or ulcer can be estimated by screening the presence of H. pylori virulence genes (i.e. vacA m1/m2, ureA and cagA) and expression levels of IL-17, FOXP3 and IFN- γ in the host." (PMID 26287606, 2015). "The ratio of FoxP3+ Treg cells to total CD4+ T cells was significantly lower in gastritis lesions (12.6±1.7%, n = 5) than in the spleen (19.0±3.8%, n = 3; P<0.01)." (PMID 18716662, 2008). "Next, within the gastric mucosa of H. pylori-infected patients, Foxp3 as well as CD25 were increased and were found to be positively correlated with the severity of gastritis." (PMID 39022746, 2024). "During H. pylori infection, forkhead box P3+ (FOXP3+) T cells detect ambient inflammatory signals such as IL-6, which is responsible for the immune response and exacerbates gastritis." (PMID 38893079, 2024). "Compared to the negative control group, H. pylori-infected gastritis patients showed elevated levels of Th17 and Treg cell transcription factors (RORγt and forkhead box protein 3 (Foxp3) mRNA) in both peripheral blood and gastric mucosa." (PMID 41035878, 2025). "First, within the gastric mucosa of patients infected with H. pylori, positive correlations between ANGPTL4 and CCL5 as well as between CCL5 and Foxp3 were found, and CCL5 was also increased and was found to be positively correlated with the severity of gastritis." (PMID 39022746, 2024). "Hence we found a positive correlation between severity of gastritis and no of Foxp3+ cells as well as IL-10 and TGF-β expression." (PMID 28286572, 2017).
Granuloma (22 papers, 2007 to 2024). A compact, organized collection of mature mononuclear phagocytes, which may be but is not necessarily accompanied by accessory features such as necrosis. "The accumulation of immature LC in LCH granulomas was associated with the expansion of FoxP3+ CD25 + CD4+ regulatory T cells both in granuloma and in the blood of patients." (PMID 18810271, 2008). "Compared to control samples, granuloma-remote CS parenchyma is characterized by significantly increased expression of HLA-DR, Treg markers FOXP3, CD25 and GITR, endothelial/stem-cell marker CD34, and global nuclei/proliferation marker Histone-H3." (PMID 38766184, 2024). "The characterization of the granulomas associated to degenerated flukes revealed a high number of type 2 macrophages (CD163+) and CD3+ T lymphocytes with a low population of Foxp3+ Treg cells." (PMID 34679889, 2021). "During chronic stages of infection, there was an approximate fourfold increase in CD4+ CD25+ Foxp3+ Tregs in colonic granulomas, evidenced by an increase in the intestinal homing markers CD103+ and CCR5+." (PMID 32692855, 2021). "The increased levels of Foxp3 and Il10 mRNA found in the encapsulated granuloma center support a local suppression of pulmonary inflammatory cells." (PMID 31015452, 2019). "Immunostaining of skin lesions showed localization of FOXP3 cells in the granulomas of both types of leprosy with a significant increase in bacilli laden lepromatous lesions." (PMID 24454972, 2014). "On the other hand, Foxp3-positive Tregs were limited to the parenchyma, granulomas and perivascular areas at 4 WPI and hardly detectable in the liver of infected aly/+ mice at 12 WPI." (PMID 22928057, 2012). "CD4+Foxp3+ T cells were increased in the granulomas and perivascular areas of the liver in the chronic phase and the impairment of granuloma maturation was observed." (PMID 22928057, 2012). "Recently, CD8+ FOXP3+ Tregs were identified in granulomas of tuberculous lymphadenitis, suggesting that they may be involved in active immunosuppression observed at the infection site." (PMID 34748560, 2021). "The anti-Foxp3 mAb yielded a nuclear and/or cytoplasmic immunostaining in lymphocytes mainly located in portal areas and in a lesser amount in the periphery of granulomas and necrotic foci." (PMID 29970179, 2018). "So the immunosuppressive effect of TGF-β in controlling the pathogenesis of schistosomiasis could be exerted maily through induction of Foxp3+ Treg cell which was shown to be responsible for the down-regulation of granuloma inflammation." (PMID 23152879, 2012). "Therefore, CD4+CD25+FoxP3+Tregs appear to control Th2 colonic granulomas during chronic infection, and are likely to play a role in containing pathology during intestinal schistosomiasis." (PMID 21858239, 2011). "Furthermore, relative increases of CD4+FoxP3+ cells within colonic granulomas are apparent during chronic disease." (PMID 21858239, 2011). "The immunohistochemical method allowed observing cells expressing Foxp3 and CD25, both in the inflammatory infiltrate and around granulomas." (PMID 25233082, 2014). "The proportion of CD4+CD25+FoxP3+Tregs: CD4+ cells in the mLN increased during chronic disease, while within colonic granulomas there was an approximate 4-fold increase." (PMID 21858239, 2011). "In the case of aly/aly mice, parasites persist within granulomas accompanied by an influx of Foxp3+ Tregs that is not seen in granulomas of WT mice." (PMID 26678994, 2016). "Preliminary data on a small subset of granulomas suggests that most of IL-10 producing T cells in the granulomas are not Foxp3+Tregs, however, larger studies are needed to address the effect of regulatory T cells on other cytokines in granulomas." (PMID 25611466, 2015). "FoxP3+ CD4+ T cells are present in increased numbers in and around granulomas." (PMID 24882950, 2014).
Granuloma (continued). "However, because the micro-environment of the intestines is favourable towards the expansion of CD4+FoxP3+Tregs, it is possible that CD4+FoxP3+Treg-mediated suppression of enteric granulomas is more apparent compared with their hepatic counterparts." (PMID 21858239, 2011). "Furthermore, immunohistochemical analysis confirmed a reduction in Foxp3-immunoreactive cells in the liver parenchyma, granulomas and perivascular neo-lymphoid areas (data not shown)." (PMID 22928057, 2012).
head and neck squamous cell carcinoma (22 papers, 2009 to 2025). A squamous cell carcinoma that arises from any of the following anatomic sites: lip and oral cavity, nasal cavity, paranasal sinuses, pharynx, larynx, and salivary glands. "High FoxP3+ T-cell counts are associated with improved prognosis in patients with head and neck squamous cell carcinoma." (PMID 32785290, 2020). "While in many solid tumour types a lower T-reg density is good for the patient, there are some exceptions, such as head and neck squamous cell carcinoma, where higher FOXP3+ T-cell density is linked to better locoregional control." (PMID 28817839, 2017). "We show that FoxP3hiCD45RA−CD4+ Treg cells [activated Treg (aTreg) cells] are the predominant cell population among tumor-infiltrating FoxP3+ T cells, and that high aTreg cell-infiltrating content is associated with reduced survival in patients with head and neck squamous cell carcinoma (HNSCC)." (PMID 27177223, 2016). "The STAT3/Foxp3 axis suppression in Tregs from head and neck squamous cell carcinoma contribute to Treg reprogramming and activation of antigen‐presenting cells, ultimately improved head and neck tumor growth delay." (PMID 36226375, 2023). "In another report, metformin decreases infiltration of FOXP3 T regulatory cells in intratumor regions, increases CD8 T cell infiltration in the peritumoral leading-edge stroma, and increases the CD8/FOXP3 ratio both in tumor and leading-edge stroma of primary head and neck squamous cell carcinoma." (PMID 40434511, 2025). "IL-33 could support the expansion of ST2+Foxp3+ Treg cells, increasing the secretion of inhibitory cytokines IL-10 and TGF-β1 in ST2+Foxp3+ Treg cells and promoting their suppressive function in head and neck squamous cell carcinoma (HNSCC)." (PMID 34177907, 2021). "In head and neck squamous cell carcinoma (HNSCC), there is a significant positive correlation between the expression of FOXP3 mRNA and CD163 mRNA and TEV-PD-L1 features." (PMID 38087360, 2023). "Concerning head and neck squamous cell carcinomas (HNSCCs), previous studies have reported findings for a wide spectrum of T cell subsets such as CD8+ cytotoxic T cells, CD4+ T helper cells, and FoxP3+ regulatory T cells." (PMID 35741089, 2022). "The expression of A2AR was correlated with the protein level of HIF‐1α, CD8, forkhead box P3 (FOXP3), and CD73 in the head and neck squamous cell carcinoma." (PMID 31365790, 2019). "For all the head and neck squamous cell carcinoma(HNSCC) types, the relationship of Foxp3 expression with RFS is not clear." (PMID 27457382, 2016).
Hodgkins lymphoma (22 papers, 2006 to 2025). A heterogeneous group of malignant lymphoid neoplasms of B-cell origin characterized histologically by the presence of Hodgkin and Reed-Sternberg (HRS) cells in the vast majority of cases. "Our result is in line with published reports that the Foxp3+TIL is positively associated with better survival in EBV-associated classic Hodgkin lymphoma and follicular lymphoma." (PMID 20064222, 2010). "Similarly, in patients with Hodgkin’s lymphoma, a decrease in Foxp3+ T cells is associated with poorer survival rates." (PMID 39000453, 2024). "Similar results have been observed in the patients with Hodgkin’s lymphoma, where a high number of Foxp3+ cells correlated with longer event free survival, and relapsed samples tended to have a lower frequency of Foxp3+ cells." (PMID 35493450, 2022). "SIRT1 showed high nuclear expression in patient samples of Hodgkin’s lymphoma; once evaluated together with FOXP3 expression, SIRT1 inhibition can decrease the actions of T-reg cells." (PMID 36230534, 2022). "Mixed cellularity cases showed predilection for focal VDR and FOXP3 expression (80% cases); whereas nodular sclerosis subtype had focal and diffuse VDR and FOXP3 expression patterns in similar proportion." (PMID 32513132, 2020). "Mixed cellularity cases showed predilection for focal VDR and FOXP3 expression (80% cases); whereas nodular sclerosis subtype had focal and diffuse patterns in similar proportion of cases 47.4 and 36.8% respectively." (PMID 32513132, 2020). "Studies of follicular lymphoma and classic Hodgkin lymphoma tumor microenvironment have shown a positive correlation between FOXP3, marker of regulatory T cells, expression and improved outcomes." (PMID 32513132, 2020). "VDR was expressed regardless of the Hodgkin disease (HD) subtype with an overall positivity of 82% cases and FOXP3 was expressed in 78%, also regardless of HD subtype." (PMID 32513132, 2020). "However, the high numbers of intratumoral FoxP3+ Treg were found to be correlated with improved survival in germinal center-like DLBCL, follicular lymphoma and classical Hodgkin's lymphoma." (PMID 22174855, 2011). "In a study on human Hodgkin lymphoma, it was shown that low FOXP3+ cell numbers correlated with negative clinical outcome." (PMID 17166272, 2006). "Foxp3+PD1+ cells have been previously reported to be rare or absent in human FL, diffuse large B-cell lymphoma, Hodgkin's disease, T-cell lymphoma normal tonsils and rLN." (PMID 29731996, 2018).
leprosy (22 papers, 2013 to 2024). Leprosy is a chronic infectious disease affecting primarily the skin and peripheral nervous system. "CD4+ subsets of Th17 cells and CD25+FOXP3+ regulatory T cells (Tregs) have been shown to play a major role in disease associated immunopathology and in stable leprosy as reported by us and others." (PMID 27035913, 2016). "Our and other studies had shown that CD4+FOXP3+T regulatory cells producing TGF-β were increased in stable lepromatous patients which may explain the anergy associated with this leprosy type." (PMID 27035913, 2016). "TGF-β and IL-10 reported to be associated with FOXP3 cells were seen in both leprosy types." (PMID 24454972, 2014). "Specific subgroups, including FoxP3+ Tregs, can modulate the immune response at leprosy pathological sites." (PMID 38440733, 2024). "Analysis of IL-10-producing FoxP3+ Tregs in different polar forms and healthy controls revealed that the number of Tregs in patients was twice that of healthy contacts, and leprosy LL/BL patients also exhibited significantly higher Treg numbers." (PMID 38440733, 2024). "We assessed the expression of PD-1 on CD4+CD25+FoxP3+ Tregs derived from leprosy patients and healthy individuals to determine if it contributes to immune suppression." (PMID 37153623, 2023). "The percentage of CD4+CD25+FoxP3+ Tregs was significantly higher in the PBMCs of lepromatous leprosy patients (12.53 ± 2.46%) compared with that in tuberculoid leprosy patients (7.15 ± 1.71%) and healthy individuals (4.42 ± 1.23%)." (PMID 37153623, 2023). "In several studies, Treg cells have been demonstrated to suppress immune responses in the periphery of leprosy patients and markers associated with Treg cells, mostly CD25, TGF-1, IL-35, CTLA4, IL-10, and FoxP3." (PMID 37153623, 2023). "In the present study, we first evaluated the percentages of CD4+CD25+FoxP3+ Tregs in the PBMCs of leprosy patients as well as healthy controls." (PMID 37153623, 2023). "The authors also evaluated the methylation status of 5’CpG islands of FOXP3 promoter using methylation-specific PCR and detected a high degree of demethylation in circulating Tregs from leprosy patients." (PMID 35722339, 2022). "Increased expression of FOXP3+ Treg in leprosy cases is related to the suppression of the body's immune system against infection." (PMID 33708252, 2021). "Increased expression of FoxP3+ is often seen in lepromatous leprosy, as well as in erythema nodosum leprosum (ENL) type leprosy reactions." (PMID 33708252, 2021). "The significant difference in FOXP3+ levels shown in this study between healthy children on endemic areas and healthy children in nonendemic areas in this study's findings may indicate the susceptibility of healthy children in endemic areas to suffer from leprosy due to immune dysregulation." (PMID 33708252, 2021). "The objective of this study was to investigate the expression of FOXP3+ Treg cells in leprosy skin lesions and to correlate their clinical forms, laboratory characteristics (CD4, CD8, and CV), and the immune reconstitution syndrome in HIV-leprosy co-infection." (PMID 34748560, 2021). "An increase in the number of FOXP3+ T cells was observed in blood leukocytes of patients with lepromatous leprosy when compared with tuberculoid leprosy." (PMID 32051758, 2020). "A recent study suggested that IL-12 and IL-23 modulate the plasticity of FoxP3+ Treg cells in leprosy, converting Treg cells into Th1 and Th17." (PMID 29883464, 2018). "The percentage of CD4+Foxp3+ Tregs also enhanced in the presence of leprosy derived Bregs, which indicated that Bregs not only converted the T effector into Tregs itself but also enhanced the Tregs activity." (PMID 30083152, 2018). "Immunostaining in 96 leprosy lesions of different forms (Indeterminate/I, TT, BT, BB, BL, LL), T1R (n = 8) and T2R (n = 2) also found an increment of Foxp3 expression in T1R compared to unreactional lesions (I, BT and LL forms)." (PMID 29883464, 2018).